S100A8 (S100 calcium binding protein A8)
Diseases named in the same sentence as S100A8 in open-access papers (continued):
Sharing a sentence is not in itself a finding about the gene and the disease.
cervical cancer (9 papers, 2013 to 2026). A primary or metastatic malignant neoplasm involving the cervix. "We confirmed this expression pattern by immunohistochemical (IHC) analysis of specimens from cervical cancer patients, showing the predominant S100A8/A9 expression n epithelial cells and myeloid cells." (PMID 41513624, 2026). "Our pan-cancer analysis of S100A8/A9 expression using TCGA and GTEx data also revealed the significantly higher expression of S100A8/A9 in tumor regions than in adjacent normal tissues in cervical cancer." (PMID 41513624, 2026). "In CaSki human cervical cancer cells S100A8/A9 treatment induces apoptosis and inhibits migration of CaSki cells; S100A8/A9 also reduced the expression of matrix metalloproteinase (MMP)-2 in CaSki cells." (PMID 25298751, 2014). "Similarly, the MP6 gene set which contains S100A8/A9 downstream of SpHK1/S1P/S1PRs has the potential to serve as a predictive marker for cervical cancer response to immune checkpoint blockers." (PMID 41513624, 2026). "Notably, S100A8/A9 demonstrated more specific expression in cervical cancer tumor regions compared to other cancer types." (PMID 41513624, 2026). "In addition, the authors examined S100A8/A9+ cells in the lymph nodes of 40 patients with cervical cancer showing higher counts in the TRL-positive and in the false-positive nodes." (PMID 36835583, 2023). "Moreover, significantly greater immunoreactivity for S100A8/A9 was observed in lymph nodes from TRL-positive cervical cancer patients than in those from TRL-negative cervical cancer patients." (PMID 32170086, 2020). "Some reports show an inhibitory effect of S100A8/A9 on metastasis of human cervical cancer cells." (PMID 25811984, 2015). "Recent work in cervical cancer has established that the HPV oncogenes E6/E7 increased the expression of a large panel of pro-inflammatory genes and S100A8, which ultimately condition the microenvironment to support tumor progression." (PMID 37174723, 2023). "Importantly, inhibition of the S1P/S1PR1 signaling pathway down-regulates the expression of S100A8/A9 and suppresses the growth of HPV-KI cells and xenograft derived from cervical cancer patient." (PMID 41513624, 2026). "The authors suggested that the false-positive lymph nodes could be explained by MDSCs-mediated premetastatic niche formation using a rat model of TRL-positive and TRL-negative cervical cancer, producing false-negative lymph nodes, which were shown to have higher numbers of S100A8/A9+ cells." (PMID 36835583, 2023).
diabetic nephropathy (9 papers, 2018 to 2025). "This study presents a robust immunoinformatics-to-validation pipeline for identifying serologically detectable B-cell epitopes from HMGB1, S100A8, and S100A9—three key DAMP proteins implicated in diabetic nephropathy." (PMID 41367913, 2025). "In diabetic nephropathy mice, S100A8/A9 inhibited by lentivirus transfected into the mice kidneys ameliorated renal interstitial fibrosis." (PMID 40384874, 2025). "Another study found that S100a8 and S100a9 were upregulated in the kidney proteome of mice with diabetic nephropathy (DN)." (PMID 39911133, 2025). "Decreased levels of miR-30b-5p, S100A8, S100A9 and regucalcin have also been described in diabetic nephropathy." (PMID 32849923, 2020). "In addition, the level of S100A8/A9 indicates the inflammatory environment of type 2 diabetic nephropathy and varying degrees of microvascular lesions in the glomeruli and retina, becoming a potential new biomarker for microcirculation defects in diabetic nephropathy." (PMID 29942307, 2018).
Granuloma (9 papers, 2010 to 2026). A compact, organized collection of mature mononuclear phagocytes, which may be but is not necessarily accompanied by accessory features such as necrosis. "S100A8/A9 heterodimer is a major component of NETs and shown to accumulate in TB-induced granulomas." (PMID 37675111, 2023). "The granuloma model allows a direct quantitative comparison of the effect of S100A8/S100A9 tetramers on leukocyte recruitment triggered by a defined inflammatory stimulus within the same mouse." (PMID 36310133, 2022). "Conversely, other chemotactic factors (i.e., S100A8/A9) mediate the accumulation of neutrophils into granulomas, exacerbating inflammation." (PMID 34561226, 2021). "Such is the case in S. japonicum infection, where S100a8 and neutrophils were found near fibrotic areas of granulomas." (PMID 31412915, 2019). "Our results showing S100a8 deficiency does not impact on M. tuberculosis lung burden, or granulomas, during early infection of C57BL/6 inbred mouse strain aligns with findings by Scott et." (PMID 38861581, 2024). "Furthermore, S100A8/A9 (belongs to the Ca2 + binding S100 protein family) levels in serum are higher in sarcoidosis patients, and monocytes and multinuclear giant cells express S100A8/A9 more cytoplasmically in granulomas." (PMID 37868478, 2023). "To confirm the biological relevance of our data obtained in vitro, we used a cutaneous granuloma model, in which two biogel “plugs” were injected into the right (addition of lipopolysaccharide (LPS) plus S100A8/S100A9‐tetramer) and the left flank (addition of LPS only) of the mice." (PMID 36310133, 2022).
myocardial ischemia (9 papers, 2013 to 2025). A disorder of cardiac function caused by insufficient blood flow to the muscle tissue of the heart. "S100A8/A9 is upregulated in response to myocardial ischemia, promoting endothelial activation, platelet aggregation, and thrombus formation." (PMID 40948795, 2025). "Then we highlight the effect of S100A8/A9 heterodimer in the early inflammatory period and the late reparative period of MI as well as myocardial ischemia/reperfusion (I/R) injury." (PMID 33282877, 2020). "One study reported that S100A8 could be a promising therapeutic target for myocardial ischemia–reperfusion injury." (PMID 35572531, 2022). "This study aims to investigate whether S100A8/A9 pretreatment enhances the paracrine therapeutic effects of hAMSCs in myocardial ischemia/reperfusion injury." (PMID 34681835, 2021). "Interestingly, six out of the seven most differentially expressed IZ genes (IL8, ARG1, S100A12, CTSL, IL1R2, S100A8) identified in our study have been previously reported in myocardial ischemia, confirming the validity of our chip analysis." (PMID 28977827, 2017). "We established a murine myocardial ischemia/reperfusion model to compare the therapeutic effects of the conditioned medium of hAMSCs with or without S100A8/A9 pretreatment." (PMID 34681835, 2021).
renal fibrosis (9 papers, 2020 to 2025). A final common manifestation of a wide variety of chronic kidney diseases characterized by glomerulosclerosis and tubulointerstitial fibrosis. "Accordingly, S100a9-/− mice were found to be protected from UUO-induced renal fibrosis independently of leucocyte infiltration and inflammation and loss of S100A8/A9 shielded TEC from UUO-induced apoptosis and epithelial-mesenchymal transition." (PMID 41318746, 2025). "Additionally, UUO-induced renal fibrosis is associated with epithelial-mesenchymal transition steps mediated by S100A8/A9." (PMID 37261287, 2023). "Mice deficient in the S100A8/A9 heterodimer are protected from renal fibrosis following UUO treatment, indicating that S100A8/A9 mediates renal fibrosis, tubular apoptosis, and renal epithelial-mesenchymal transition post-UUO." (PMID 40877572, 2025). "Deficiency of S100A8/A9 protects tubular epithelial cells from the UUO-induced apoptosis of tubular epithelial cells and renal fibrosis by inhibiting epithelial–mesenchymal transition." (PMID 36768433, 2023). "S100A8/A9 mediates renal fibrosis, tubular apoptosis, and crucial events for epithelial-mesenchymal transition in the kidney after UUO." (PMID 33117389, 2020). "Tasquinimod and paquinimod blocked the S100a8/a9‐Tlr4‐Nfκb signaling pathway, improved renal function, and reduced mortality, and also decreased inflammatory monocytes infiltration, ameliorated kidney injury phenotype, and prevented long‐term renal fibrosis." (PMID 35112806, 2022). "As two members of DAMP, S100A8 and S100A9, were reported to correlate with the onset and progression of bone marrow fibrosis and renal fibrosis." (PMID 36429008, 2022). "Adult S100A9-/- mice lacking the S100A8/A9 heterodimer that were subjected to UUO were protected from renal fibrosis." (PMID 33117389, 2020).
squamous cell carcinoma (9 papers, 2013 to 2025). A carcinoma arising from squamous epithelial cells. "Mucosal epithelium, where squamous cell carcinoma originates from, is known to have high level of S100A8 and S100A9 at physiological conditions, which was reported to be present in the tumor as well." (PMID 32733643, 2020). "The expression level of S100A8/S100A9 measured in three squamous cell carcinomas (SCC) cell lines and their corresponding xenografts, as well as in 257 SCC tissues." (PMID 31208368, 2019). "While upregulated in many cancers, S100A8/A9 is downregulated in squamous cell carcinomas of the cervix, esophagus, and the head and neck (HNSCC)." (PMID 26883112, 2016). "Therefore, we examined the expression of S100A8/S100A9 in squamous cell carcinoma cell lines A431, HCC94 and FaDu." (PMID 31208368, 2019). "S100A8/A9-mediated control of the G2/M cell cycle checkpoint is, therefore, a likely suppressive mechanism in human squamous cell carcinomas and may suggest new therapeutic approaches." (PMID 23874958, 2013). "Aberrant expression of S100A8/S100A9 complex was also detected in a variety of cancer tissues, including in squamous cell carcinomas of the esophagus, oral cavity, and cervix." (PMID 31208368, 2019). "S100A8/A9 levels are generally low or not detectable in squamous carcinoma cells, whereas in inflammatory or hyperproliferative oral lesions and HNSCC tissues, S100A8/A9 complex is markedly down-regulated at both mRNA and protein levels compared to normal mucosa." (PMID 23874958, 2013).
B cell lymphomas (8 papers, 2013 to 2024). "A recent report found that S100A8 could promote chemoresistance to adriamycin and vincristine by enhancing autophagy in B-cell lymphoma cells." (PMID 35371990, 2022).
endotoxemia (8 papers, 2012 to 2025). "Taken together, these results indicate that S100A8/A9 has a direct pathogenic role in systolic LV dysfunction during endotoxemia, which can be reversed by the ABR-238901 treatment." (PMID 37773186, 2023). "Following induction of endotoxemia, the mice experienced a rapid loss in bodyweight, which was partially reversed by S100A8/A9 blockade." (PMID 37773186, 2023). "Previous in vivo studies that implicated TLR4 in S100A8 and S100A8/A9 mediated inflammation have done so largely in the context of endotoxemia, where TLR4 would be readily activated." (PMID 25706559, 2015). "We used an experimental model of endotoxemia to investigate whether S100A8/A9 has a direct pathogenic role and may be used as a therapeutic target in SIMD." (PMID 37773186, 2023). "have previously shown a direct relationship between S100A8/A9 and mortality in an experimental model of endotoxemia." (PMID 37773186, 2023). "Taken together, these results confirm the pro-inflammatory and cardio-depressant role of S100A8/A9 in endotoxemia and confirm the target specificity of the ABR-238901 treatment." (PMID 37773186, 2023). "Here, we provide proof of concept that S100A8/A9 blockade reduces inflammation and cardiac dysfunction in endotoxemia." (PMID 37773186, 2023). "It has previously been demonstrated that cardiac overexpression of S100A8/A9 exacerbates myocardial dysfunction during endotoxemia, supporting a mechanistic link between elevated levels of the protein and impaired contractility." (PMID 37773186, 2023). "Pharmacological administration of S100A8 to mice at the onset of a model of endotoxemia has been reported to significantly increase survival rate." (PMID 28405616, 2017). "Very recently it was shown that S100A8 administration attenuated inflammation and injury in a mouse model of endotoxemia." (PMID 23874727, 2013). "In a mouse model of endotoxemia, LPS rapidly induced S100A8/A9 release and acute cardiac depression, while genetic deficiency of S100A9 or pharmacological blockade of S100A8/A9 with ABR-238901 prevented or reversed myocardial dysfunction and reduced systemic inflammation." (PMID 41293242, 2025). "Further, we explored whether S100A8/A9 blockade with a small molecule inhibitor could be used as a potential treatment against systemic inflammation and acute myocardial dysfunction in an experimental model of endotoxemia." (PMID 37773186, 2023). "We used S100A8/A9 blockade with the small-molecule inhibitor ABR-238901 and S100A9−/− mice for therapeutic and mechanistic studies on endotoxemia-induced cardiac dysfunction in mice." (PMID 37773186, 2023). "Moreover, exogenous S100A8 administration reduced PMN infiltration and attenuated tissue damage in a murine model of LPS-induces endotoxemia." (PMID 34966382, 2021).
head and neck squamous cell carcinoma (8 papers, 2016 to 2025). A squamous cell carcinoma that arises from any of the following anatomic sites: lip and oral cavity, nasal cavity, paranasal sinuses, pharynx, larynx, and salivary glands. "Downregulation of S100A8 in head and neck squamous cell carcinoma is associated with poor prognosis and lower rates of survival." (PMID 29868478, 2018). "In head and neck squamous cell carcinoma, S100A8/A9 is downregulated in mRNA and protein levels, and the loss of S100A8/A9 heterodimer is related to poor differentiation and the increased risk of metastasis." (PMID 38093319, 2023). "It has been demonstrated that S100A8/9 obeys the tissue-based pattern in cancer progression, and its up regulation was reported in colon, lung and gastrointestinal cancers; however its down-regulation was reported in head and neck squamous cell carcinoma." (PMID 31528166, 2019). "In head and neck squamous cell carcinoma, S100A8/A9 (calprotectin) could suppress cell growth by inducing G2/M cell cycle checkpoint arrest." (PMID 27297407, 2016). "Prior research demonstrated that downregulation of S100A8 and S100A9 was correlated with a decrease in prognosis in inflammatory conditions and cancers involving the oral cavity, such as head and neck squamous cell carcinoma." (PMID 40486046, 2025). "In different cancers, S100A8/A9 expression varies with cell and tissue of origin, but it is widely reported to be downregulated in cells from head and neck squamous cell carcinoma (HNSCC)." (PMID 26883112, 2016). "S100A8 is reported to regulate autophagy-dependent ferroptosis in experimental subarachnoid hemorrhage, and S100A9 may also play regulatory roles in ferroptosis but lack “wet” experimental validation in head and neck squamous cell carcinoma." (PMID 37691822, 2023).
inflammatory skin disease (8 papers, 2011 to 2025). Inflammatory skin disorders covers a broad category that includes many conditions ranging in severity, from mild itching to grave medical health complications These disorders are common in people of all ages and races. "In particular, S100a8 and S100a9 have been shown to be increased in inflammatory skin diseases, suggesting that the PAC1R KO mice have skin inflammation due to defective aquaporin action." (PMID 36902003, 2023). "It is up-regulated in inflammatory skin disorders, while S100A8 and S100A9 form a complex that displays cytostatic and anti-microbial activities." (PMID 26717000, 2015). "Consistent with our FSHD findings, KRT16 and S100A8 are also up-regulated together in inflammatory skin disorders; additionally, the pattern of increased S100A8 with decreased PROC is seen here in FSHD as well as in IBD and several other chronic inflammatory disorders." (PMID 33228131, 2020). "S100A8/A9 could be a part of a positive feedback mechanism in the initiation and amplification of inflammatory skin diseases through inducing proinflammatory cytokine production as well as proliferation of keratinocytes." (PMID 27537874, 2016).
mastitis (8 papers, 2013 to 2025). Inflammation of breast tissue during lactation or postpartum due to an obstructed duct or infection. "This suggests that in the context of mastitis, upregulation of S100A8, S100A9, and S100A12 enhances the production of pro-inflammatory cytokines and Chemokines to maintain host homeostasis." (PMID 41156687, 2025). "The transferration of S100A8-riched EVs to acceptor cells orchestrates the activation of neutrophil degranulation, thus, can contribute to the innate immune response of clinical mastitis." (PMID 36611779, 2023). "Another significant feature of the mammary host response was the significant enrichment of the DEGs involved in chronic inflammatory response (CXCL13, IDO1 and S100A8) that led to the mastitis phenotype." (PMID 28081235, 2017). "Protein S100-A9, Protein S100-A8, Chitinase-3-like protein 1, Haptoglobin, Integrin beta-2, and Chloride intracellular channel protein 1 were more abundant in milk-derived EVs for clinical mastitis." (PMID 36611779, 2023). "As EVs cargo, S100A8/A9 enrichment may be attributed to the formation of NETs, which widely occur in clinical mastitis for capturing and killing invading pathogens." (PMID 36611779, 2023). "Next to the importance for the newborn infant, antimicrobially active amounts of S100A8/A9 in BM might also be important for the mother by protecting from lactational mastitis, especially given the fact that Staphylococci and Streptococci are the most common pathogens found in mastitis." (PMID 29326708, 2017). "Many of the genes within this category have previously been identified as being involved in the immune response to mastitis, including LBP, STAT3, S100A8 and SOD2." (PMID 23324411, 2013). "In the present study, proteins S100A12, S100A8 and S100A9, were up-regulated by 11.17, 5.1 and 5.1 folds in the mastitis-infected mammary glands, which is consistent with the previous report, further demonstrating their roles in the immune response to pathogen infection." (PMID 25273983, 2014).
metastatic melanoma (8 papers, 2010 to 2024). A melanoma that has spread from its primary site to another anatomic site. "KRT16 is linked to better outcomes in metastatic melanoma, while low levels of S100A8/A9 correlate with advanced disease stages." (PMID 39766071, 2024). "The tumor microenvironment-associated protein S100A8/A9 serves as a novel prognostic marker for metastasis and survival of metastatic melanoma patients and predicts response to immunotherapy with pembrolizumab." (PMID 31806053, 2019). "Our results highlight that an increased level of circulating S100A8/A9 during ICIs treatment impair clinical outcome of metastatic melanoma patients." (PMID 39700646, 2024). "•Our study warrants for testing therapies targeting S100A8/A9 and other NET-associated factors in metastatic melanoma." (PMID 39700646, 2024). "Moreover, our study warrants for testing therapies targeting S100A8/A9 and other NET-associated factors linked to neutrophils’ immunosuppressive properties in metastatic melanoma." (PMID 39700646, 2024). "•Increased levels of circulating S100A8/A9 during ICI and accumulation of TANs impair clinical outcome of metastatic melanoma." (PMID 39700646, 2024). "Increased expression of the two downstream regulators of ID1, S100A8 and S100A9 levels was also observed (1.8- and 1.7-fold higher and up to 3.1- and 2.7-fold, respectively) in CD11B+ PBMCs from patients with metastatic melanoma compared with healthy, age-matched controls (unpaired t-test, P<0.01)." (PMID 25924227, 2015).